ZNF687 (zinc finger protein 687)
Description:
May be involved in transcriptional regulation.
Synonyms: KIAA1441; PDB6
Tractability: PROTAC: UniProt records ubiquitination sites on it; ubiquitination databases record sites on it; its protein half-life has been measured.
Gene: Protein-coding gene on chromosome 1 (151,281,502 to 151,292,180, forward strand). Ensembl gene ENSG00000143373.
Subcellular location: Cytoplasm; Nucleus
Subcellular location (Human Protein Atlas): Nucleoplasm
Pathways (Reactome):
Chromatin organization: Interaction of NuRD complexes with transcription factors
Gene Ontology:
Molecular function: protein binding; DNA-binding transcription factor activity
Biological process: regulation of DNA-templated transcription
Cellular component: cytoplasm; nucleoplasm; nucleus
Genetic constraint (gnomAD): Loss-of-function variants: 14 observed, 74.73 expected, observed/expected ratio (o/e) 0.19, 90% interval 0.12 to 0.29. The upper end of that interval is the gene's LOEUF score, 0.29, which puts it in group 1 of 6, group 1 being the genes least tolerant of losing a copy. Missense variants: 1,412 observed, 1,681 expected, observed/expected ratio (o/e) 0.84, 90% interval 0.8 to 0.88. Synonymous variants: 673 observed, 663.65 expected, observed/expected ratio (o/e) 1.01, 90% interval 0.95 to 1.08.
Homologues: Orthologues: chimpanzee ZNF687 (99% identical), macaque ZNF687 (98% identical), pig ZNF687 (91% identical), rabbit ZNF687 (90% identical), dog ZNF687 (89% identical), rat Zfp687 (87% identical), mouse Zfp687 (86% identical), guinea pig ZNF687 (86% identical), tropical clawed frog znf687 (52% identical), zebrafish znf687b (39% identical), zebrafish znf687a (35% identical). Paralogues in human: ZNF592 (32% identical), PRDM2 (14% identical), ZNF287 (10% identical), ZNF214 (10% identical), ZNF527 (10% identical), ZKSCAN7 (10% identical), ZNF407 (10% identical), ZBTB17 (10% identical), ZNF852 (10% identical), ZNF34 (10% identical), WIZ (10% identical), ZNF572 (9% identical), and 38 more.
Diseases named in the same sentence as ZNF687 in open-access papers:
ZNF687 is named in the same sentence as 18 diseases in open-access papers, as found by Europe PMC text mining. Sharing a sentence is not in itself a finding about the gene and the disease. The quoted sentences say what the papers report.
Paget’s disease of bone (8 papers, 2017 to 2025). "It is interesting to note that mutations in another member of the ZNF genes, specifically ZNF687, have been reported in a peculiar subgroup of severe Paget’s disease of bone associated with giant cell tumor." (PMID 32671420, 2020). "On the contrary, we recently highlighted that giant cell tumour, when arising on Paget’s disease of bone – a disorder of bone remodelling – shows a different genetic signature characterised by a germline mutation in the ZNF687 gene." (PMID 29609578, 2018). "Overexpression of ZNF687 has been observed in tumor tissue of individual giant cell tumor of bone associated with Paget disease of bone, and this high expression is also observed in the peripheral blood of patients affected with Paget disease." (PMID 29108258, 2017). "Recently, we reported a founder germline mutation (p.Pro937Arg) in the ZNF687 gene as responsible for the Giant Cell Tumor arising on Paget's disease of bone." (PMID 28968976, 2017). "Zinc finger protein 687 (ZNF687), a transcription factor implicated in osteoblast/osteoclast differentiation and linked to Paget’s disease of bone, has unclear mechanisms in bone metabolism." (PMID 40076693, 2025).
giant cell tumor (6 papers, 2017 to 2023). A benign, intermediate, or malignant tumor that arises from the bone or soft tissue. "PDB patients with the ZNF687 mutation, if untreated, undergo giant cell tumor degeneration." (PMID 36918542, 2023). "Besides, we investigated the presence of mutation in the coding region of the ZNF687 gene that we recently identified in giant cell tumour complicating Paget’s disease of bone." (PMID 29609578, 2018). "Also, germline mutations in the ZNF687 and PFN1 genes have been associated to severe, early onset, polyostotic PDB with increased susceptibly to neoplastic degeneration, particularly giant cell tumor." (PMID 36035996, 2022).
giant cell tumor of bone (4 papers, 2017 to 2025). "Zinc finger protein 687 (ZNF687), identified as a C2H2 zinc finger protein, has been found to be mutated and upregulated in giant cell tumor of bone and acute myeloid leukemia, suggesting an oncogenic role for ZNF687 in cancer." (PMID 28737756, 2017). "Zinc finger protein 687 (ZNF687) has previously been discovered as a potential oncogene in individuals with giant cell tumors of the bone, acute myeloid leukemia, and hepatocellular carcinoma." (PMID 36944484, 2023).
hepatocellular carcinoma (4 papers, 2017 to 2023). A malignant tumor that arises from hepatocytes. "Recent studies indicate that ZNF687, which is elevated and mutated in giant cell tumors, hepatocellular carcinoma (HCC), acute myeloid leukemia, and bone cancer, has an oncogenic function in cancer." (PMID 36944484, 2023). "Herein, we report that ZNF687 was markedly upregulated in hepatocellular carcinoma (HCC) cell lines and HCC tissues, and was significantly correlated with relapse-free survival in HCC." (PMID 28737756, 2017).
lung adenocarcinoma (2 papers, 2023 to 2024). A carcinoma that arises from the lung and is characterized by the presence of malignant glandular epithelial cells. "Association of ZNF687 expression with clinicopathological characteristics of individuals with lung adenocarcinoma (LUAD)." (PMID 36944484, 2023). "Oncogenic zinc finger protein ZNF687 activates PI3K/Akt/mTOR signaling pathway to accelerate lung adenocarcinoma cell proliferation and tumor progression." (PMID 39717098, 2024). "ZNF687 expression sequences in lung adenocarcinoma (LUAD) and matched paratumor tissues were shown in the immunohistochemistry (IHC) analysis." (PMID 36944484, 2023). "ZNF687 expression patterns in lung adenocarcinoma (LUAD) and paratumor tissues microarray were revealed in the immunohistochemistry (IHC) analysis." (PMID 36944484, 2023).
amyotrophic lateral sclerosis (1 paper, 2022). Amyotrophic lateral sclerosis (ALS) is a neurodegenerative disease characterized by progressive muscular paralysis reflecting degeneration of motor neurons in the primary motor cortex, corticospinal tracts, brainstem and spinal cord. "Additionally, some cases of PDB-like syndromes have been attributed to mutations in VCP, TNFRSF11A, TNFRSF11B, HNRNPA2B1, HNRNPA1, ZNF687 and PFN1, most of which are known to involved in the amyotrophic lateral sclerosis (ALS) and nuclear factor kappa B (NF-kB) signaling pathways." (PMID 35355568, 2022).
bone tumors (1 paper, 2023). "Since PDB patients with the ZNF687 mutation are prone to developing giant cell tumor degeneration, we looked for bone tumors in Zfp687 mutant mice." (PMID 36918542, 2023).
Cirrhosis (1 paper, 2017). A chronic disorder of the liver in which liver tissue becomes scarred and is partially replaced by regenerative nodules and fibrotic tissue resulting in loss of liver function. "However, analysis of publicly available data sets showed that ZNF687 mRNA expression was significantly upregulated in HCC tissues compared with adjacent tumor tissues or cirrhosis liver tissues (GSE57957, GSE56140 and TCGA)." (PMID 28737756, 2017).
lung carcinoma (1 paper, 2023). "Using bioinformatic analysis, we found that ZNF687 was related to the PIP3‐activated AKT signaling pathway, a pathway frequently involved in human cancers, particularly lung cancer." (PMID 36944484, 2023).
Osteopenia (1 paper, 2025). Osteopenia is a term to define bone density that is not normal but also not as low as osteoporosis. "Given its emergent role in osteoblast differentiation and bone development, ZNF687 could represent a promising target for therapeutic purposes in human bone-related disorders, characterized by defective (e.g., osteoporosis and osteopenia) or excessive bone formation (e.g., osteopetrosis and PDB)." (PMID 40076693, 2025).
tumor (6 papers, 2017 to 2024). "Then, we excluded the two-hit model in the H3F3A gene as trigger event for the GCT transformation of the pagetic bone performing somatic molecular analysis on 5 GCT/PDB tumor tissues carrying the ZNF687 germline mutation." (PMID 28968976, 2017). "An IHC analysis of 20 paired tumor and paratumor specimens revealed that ZNF687 was strongly expressed in cancer tissues." (PMID 36944484, 2023). "A xenograft tumor model was used to examine the biological effect of ZNF687 on HCC progression." (PMID 28737756, 2017). "The activation of the PI3K/AKT signaling pathway by upregulated ZNF687 increased the proliferation of LUAD cells and tumor progression." (PMID 36944484, 2023). "Conversely, ZNF687 knockdown decreased LUAD cell proliferation and tumor progression." (PMID 36944484, 2023). "Consistent with TCGA analysis, the expression of both ZNF687 mRNA and protein was markedly higher in the eight HCC cell lines and ten HCC tissues than in the two primary normal human liver cell lines and the matched adjacent non-tumor tissues, respectively." (PMID 28737756, 2017).
cancer (3 papers, 2017 to 2025). A tumor composed of atypical neoplastic, often pleomorphic cells that invade other tissues. "Subsequently, rescue experiments indicated that LY294002 inhibited and attenuated the cancer promotion impact via ZNF687 overexpression." (PMID 36944484, 2023). "However, the clinical significance and precise role of ZNF687 in cancer progression are largely unknown." (PMID 28737756, 2017). "However, 50 transcription factors displayed similar interactions with SWI/SNF in the two cancer types, such as several zinc-finger transcription factors (ZNF512, ZNF598, ZNF609, ZNF687, and ZNF709), CTCF, ELF2, and YBX1, indicating shared gene regulation networks." (PMID 40988026, 2025).
ZNF687 also shares sentences with these, for which no sentence is quoted: Paget disease (3 papers); acute myeloid leukemia (2); breast carcinoma (1); liver cancer (1); osteopetrosis (1); osteoporosis (1).